AKT2 (AKT serine/threonine kinase 2)
Diseases named in the same sentence as AKT2 in open-access papers (continued):
Sharing a sentence is not in itself a finding about the gene and the disease.
tumor (continued). "miR-124 may act as a tumor suppressor to inhibit BC development by targeting AKT2, and ERα is required for E2 upregulated-AKT2 expression, which can bereversedby miR-124 in ERα-positive BC cells." (PMID 27175587, 2016). "Finally, overexpression of miR-124 in MCF7 cells significantly suppressed tumor growth and angiogenesis by targeting AKT2." (PMID 27175587, 2016). "AKT2 is related to tumor growth and metastasis in HCC, and is activated by PI3K pathway." (PMID 27143508, 2016). "In addition, we found that the Classical markers FGFR3, PDGFA, EGFR, AKT-2 and Nestin are highly expressed in intracranial tumor tissue derived from bulk tumor cells and Sp-GSCs, while there is lower expression in Ad-GSC intracranial tumors." (PMID 25955030, 2015). "Evidence also suggests that the PI3K/Akt pathway may promote metastasis and invasion in these tumor cells: knockdown of Akt1, Akt2, or Akt3 impairs neuroendocrine cell invasion, and knockdown of PTEN promotes liver metastasis in mouse xenograft models." (PMID 26793165, 2015). "We tested the AKT2-dependent effects of ectopic expression of miR-612 on tumor growth in vivo." (PMID 26158514, 2015). "Furthermore, knock out of Pten in the liver of Akt null mice delays the onset of both fatty liver and tumor formation supporting a role for AKT2 in this process and the notion that the induction of lipogenesis is needed to drive tumor formation." (PMID 25502566, 2014). "In addition, ablation of Akt1 in MMTV-neu or MMTV-PyMT transgenics inhibited tumor formation while the ablation of Akt2 accelerated tumor formation." (PMID 23919516, 2013). "Patients whose tumours showed strong Akt2 expression and had pAkt (pAkt-Thr308 and/or pAkt-Ser473) detectable in the cytoplasm as well as nucleus (n+c), exhibited improved time to progression (TTP) and overall survival from the initiation of trastuzumab therapy (OSt)." (PMID 22842582, 2012). "Interestingly, AKT2 has been shown to be transcriptionally regulated by the master regulator of epithelial-mesenchymal transition (EMT), Twist, and is associated with tumor progression and metastasis." (PMID 22666248, 2012). "Furthermore, co-treatment with BEZ235 and PS more effectively blocked tumor growth of primary PDAC heterotransplants (possessing K-RAS mutation and AKT2 amplification) subcutaneously implanted in the nude mice than each agent alone." (PMID 23232026, 2012). "Among the three human isoforms Akt1, Akt2, and Akt3, it has been suggested that Akt1 may have an important role in tumor initiation and tumor growth." (PMID 18184439, 2008). "This paradox may be explained by either different sensitivity of the antibodies or by crossreactivity of the phospho-Akt-1 (ser473) antibody with another activated isoform present in the tumour, like Akt-2 or Akt-3." (PMID 11870534, 2002). "Immunohistochemical staining confirmed the presence of CD45.1+ transferred T cells, showing that Akt2-OE CTLs could penetrate the tumor core, while control or Akt1-OE CTLs were primarily confined to the stroma (CD45.1 staining in brown, indicated by yellow arrow)." (PMID 40139836, 2025). "A low level of akt2-a in reproductive castes may inhibit tumour invasion and metastasis." (PMID 36362447, 2022). "Here, we added a new piece to the complex miR-126 puzzle, by demonstrating specific downregulation of another component of this cascade, namely AKT2, thus further strengthening the hypothesis that miR-126-3p tumor suppressor activity relies on the inhibition of PIK3/AKT signaling." (PMID 35628294, 2022). "However, systemic deletion of Akt1 but not Akt2 inhibited lung metastasis through impairment of mobilization and survival of tumor-associated neutrophils and neutrophil-specific deletion of Akt1 suppressed metastasis." (PMID 34298660, 2021).
tumor (continued). "Furthermore, within the mTOR signalling pathway, we found several oncogenes, including mTOR, AKT1 and AKT2 and tumour suppressor genes that were significantly upregulated for subtype-1 tumours and all of which have previously been linked to pancreatic carcinogenesis." (PMID 34506537, 2021). "Another interesting finding in our data is that tumors in the Amp signature cluster showed amplifications in AKT3 whereas tumors with the Del signature had amplifications in AKT2, suggesting that both tumor types may utilize the AKT survival pathway for tumorigenesis." (PMID 33800889, 2021). "In addition, as protein kinase Akt2 has been reported to be able to promote PKM2 phosphorylation in tumor cells, shikonin may inhibit PKM2 phosphorylation through suppressing the expression and activity of such protein kinase." (PMID 30266938, 2018). "Therefore, silencing of AKT2 through siRNA could be a promising strategy to impair tumor development and recurrence." (PMID 29667444, 2018). "In mice exposed to the lung carcinogen (NNK) loss of Akt1 or Akt2 decreased lung tumor multiplicity but did not decrease lung tumor volume while loss of Akt1 but not Akt2 in K-ras transgenic mice significantly decreased tumor multiplicity and tumor volume." (PMID 26654940, 2016). "Thus, forced expression of AKT2 totally blocked the inhibitory effect of miR-612 on tumor size." (PMID 26158514, 2015). "A recent study indicates that in PTEN-deficient tumours, AKT2 is the active isoform but not AKT1." (PMID 26528548, 2015). "Furthermore, we found that this anti-HER2 targeted treatment-associated positive effect was even more powerful in patients whose tumours also had strong expression of Akt2 as well as cytoplasmic and nuclear localization of pAkt (pAkt Thr308 and/or pAkt Ser473)." (PMID 22842582, 2012). "Notably, from the integrated analysis of the TMAs we found that AKT activation was more frequently observed in tumours showing aberrant expression of more than a single gene within the PI3K pathway (PTEN loss, or overexpression of AKT1, AKT2, p110α respectively)." (PMID 22363436, 2012). "OSm for tumours with strong expression of total Akt2 and pAkt Thr308-n+c vs. all other tumours was 59.2 vs. 24.1 months, P=0.006, HR 0.39, 95% CI 0.22–0.69; and it was 59.2 vs. 24.5 months, P=0.008, HR 0.45, 95% CI 0.26–0.79 for strong expression of total Akt2 and pAkt Ser473-n+c." (PMID 22842582, 2012). "Oxidative phosphorylation components (NDFs, COXs, TCIRG1, LHPP) and chemical carcinogenesis pathways involving reactive oxygen species (CYP1B1, GSTs, AKT2, IKBKB, MAPK3, MAP2K2) exacerbate DNA damage and promote tumour aggressiveness." (PMID 41007296, 2025). "Key predictors included clinical variables (age, tumor size, NPI, radiotherapy) and molecular markers (ATM, HERC2, AKT2, FOXO3, CYP3A43)." (PMID 41300329, 2025). "Feature selection was performed using the Boruta algorithm, which revealed that both clinical parameters (e.g., age, tumor size, NPI, radiotherapy) and transcriptomic biomarkers (e.g., ATM, HERC2, AKT2, CYP3A43, FOXO3) provided strong prognostic contributions." (PMID 41300329, 2025). "Using our quantitative iMALDI-MS assay, we observed significant inter-tumor variability in the amount of AKT1 and AKT2 protein, with as much as a 4-fold difference among PIK3CA-mutated tumors." (PMID 38954770, 2024). "Mechanistically, the alteration of CAFs-derived AKT2/CCTα axis and its-activated intratumoral JAK2/STAT3 pathway induces the resistance of FAK inhibitor in tumor treatment." (PMID 38280862, 2024). "LRP1, AKT2, PI3, IL27RA, OBP2A, and PAEP were found to be more expressed in OC tumour samples than in normal tissues." (PMID 39063239, 2024). "miR‐182‐5p indirectly inhibits AKT2 activity by targeting FLOT1, resulting in increased activity of the downstream transcription factor FOXO3a, thereby suppressing tumor cell proliferation." (PMID 39092291, 2024).
tumor (continued). "Research indicates that in NSCLC cells resistant to EGFR-TKIs, diminished expression of SFRP5 triggers the activation of the Wnt pathway, facilitating tumor advancement and drug resistance via EMT and Akt2 signaling pathways mediated by TWIST." (PMID 39196297, 2024). "The mice on the doxycycline chow had significantly reduced tumor growth compared to the regular chow-fed mice, together showing that AKT1 drives tumor cell proliferation, whereas AKT1 and AKT2 both contribute to anchorage-independent growth." (PMID 37894325, 2023). "Members of the AKT family include three isoforms, AKT1, AKT2, and AKT3, which are involved in different mechanisms of tumor progression." (PMID 36927770, 2023). "In stage 7 (sm b stage), PI3K-AKT signaling and EMT signaling (e.g., AKT2/3, COL2A1, etc.)were dominant, of which EMT signaling is involved in tumor-initiation and motility." (PMID 36966136, 2023). "In the D5 (DAC stage), mTOR signaling (e.g., AKT2 and RPTOR) and EGFR signaling (e.g., EGFR and GSK3B) were overrepresented, implying the progression of cancer and tumor growth." (PMID 36991000, 2023). "Our results show that AKT2 depletion consistently inhibits invasive and migratory behaviors, while AKT1 depletion reduces cellular proliferation and tumor growth." (PMID 37894325, 2023). "MiR-193a-3p, a tumor suppressor, targets ALKBH5 exerting an anti-tumor effect by restraining the growth of glioma cells and promoting apoptosis via inhibiting the AKT2 pathway." (PMID 38072944, 2023). "In the case of TNBC, nanobodies against tumor-specific antigens such as TNF-α, EGFR, CD3, CTLA-4, STAT-3, AKT2 among others, have been generated and tested for targeting cancer cells." (PMID 36507540, 2022). "Based on AKT1/AKT2 and AKT1/AKT3 ratios, we define four AKT classes which were related to patients’ survival, tumor morphology and BRCA1 expression." (PMID 35053468, 2022). "AKT isotypes, such as AKT1, AKT2 and AKT3, have been suggested as therapeutic targets for angiogenesis-related abnormalities such as tumor or ischemic injury." (PMID 36286049, 2022). "According to the boxplots analysis, tumor expression of AKT1, AKT2, and PDK1 is higher than the normal." (PMID 35634241, 2022). "Targeting the β-catenin/AKT2/CAD axis repressed cell proliferation and tumor development driven by oncogenic β-catenin." (PMID 36122209, 2022). "Based on our collected kidney normal and RCC samples, we compared the expression of AKT1 (AKT), AKT2 and AKT3 in RCC tumor tissues versus normal tissues." (PMID 34384473, 2021). "Then, we investigated AKT2 levels in human cancer tissues, and higher mRNA levels of AKT2 were found in NSCLC tissues compared with adjacent non-tumor tissues." (PMID 33015042, 2020). "There are three subtypes of AKT, namely AKT1, AKT2, and AKT3, among which AKT2 is responsible for tumor progression and metastasis through regulating EMT-related proteins." (PMID 33123457, 2020). "The increased expression of EMT genes (AKT2, TWIST, and mTOR) in tdTomato− tumors, in CTCs and in mammospheres, highlights the importance of AKT2 in tumor growth and CSC malignancy." (PMID 31357505, 2019). "We validated the focal status of gene amplification (size < 10Mb) for 2 tumours (focal amplification of CCND1 for tumour T8 and focal amplifications of DDR2, AKT2 and MDM2 for tumour T16) using array comparative genomic hybridization." (PMID 29416628, 2018). "VIM, TWIST1, AKT2, and SNAI1 are expressed in CRC pathological tissues, where they promote tumor metastasis by inducing the EMT process." (PMID 28030836, 2017). "Indeed, our previous experiments had already shown that the individual distribution of AKT kinases and SGK-1 differ between individual tissues, which might explain why shc-1;akt-1 germline tumor are potently suppressed by RNAi down-regulation of either akt-2 or sgk-1." (PMID 28549065, 2017).
tumor (continued). "For example, although both AKT1 and AKT2 are required for primary tumor growth, AKT2 appears to promote tumor metastasis, while AKT1 has an inhibitory role in tumor invasion and metastasis." (PMID 26895380, 2016). "The selection of a pan-AKT inhibitor assumes that all 3 AKT isoforms promote tumor formation and progression, however, data from this current study and other studies suggest that AKT1 and AKT2 have opposite effects on lung tumorigenesis." (PMID 26654940, 2016). "The stem cell marker ALDH1 was found to be the most prominent expressed gene with an expression rate of 85.7%, whereas AKT2 and PIK3CA were found in 50.0% and 42.9% of the tumour cells, respectively." (PMID 27302574, 2016). "miRNAs modulate the expression of numerous metabolic factors and enzymes, such as SREBF2, AKT2, G6PD, CPS1, FADS1, and ETNK1, which alter tumor cell responses to chemotherapeutic treatments." (PMID 27861141, 2016). "There was increased expression in the HCC tumor compared to the benign adjacent tissue in the following proportions of HCCs: AKT1 (48.2%), AKT2 (29.1%) and AKT3 (70.0%)." (PMID 27611696, 2016). "We also conducted IHC experiments of AKT2, AKT3, PKM2 and HK2 levels in xenograft tumor tissue sections." (PMID 26512921, 2015). "Within the cohort of mice bearing miR-184-overexpressing tumour cells, the expressions of a number of miR-184 targets (e.g., AKT2, GSK3A and S6K2) were reduced in three out of four mice when compared to the control tumours." (PMID 26070602, 2015). "Our data show that both Akt1 and Akt2 are expressed in ATII cells, the putative tumor initiating cells, but that Akt1 is expressed at a higher level in these cells." (PMID 24722238, 2014). "Moreover, loss of Akt1 or Akt2 did not alter tumor histology or cytokeratin expression." (PMID 23919516, 2013). "A high-level CCND3 tumor (Case OC-07) showed co-amplification of MYC and AKT2; and a high-level MYC tumor (OC-08) was co-amplified for JAK2, FGFR3, and MYB." (PMID 23289505, 2013). "Patients with tumours with strong Akt2 and pAkt Thr308 (n+c) had superior TTP (17.0 vs. 7.6 months, P=0.024; HR 0.52) and OSt (51.8 vs. 16.8 months, P=0.0009; HR 0.34) compared to other tumours." (PMID 22842582, 2012). "In a drug-resistant MDA-MB-468 xenografts, systemic administration led to superior tumor accumulation, effective AKT2 knockdown, and significant tumor regression via the p21/Caspase-3 apoptotic axis, without systemic toxicity." (PMID 42284488, 2026). "Sorted Akt2T309A-OE CTLs exhibited impaired antitumor activity, as evidenced by sustained bioluminescence signals and a lack of tumor regression, in contrast to the robust tumor clearance observed with Akt2-OE CTLs." (PMID 40139836, 2025). "We observed a reduction in tumor size in the group of mice receiving Akt2-OE CTLs, but no significant change was seen in the groups receiving control or Akt1-OE CTLs." (PMID 40139836, 2025). "Although PLX4032 significantly decelerated tumor growth, the overexpression of AKT2-206, rather than AKT2-210, reversed the growth inhibition." (PMID 40681872, 2025). "Specifically, our data also indicate that FAK inhibition-stimulated the activation of AKT2/CCTα axis and PC production uniquely occurred in CAFs, while not in tumor cells." (PMID 38280862, 2024). "In addition, anti-C5aR1 Ab reduced PFKM ubiquitination in peritoneal macrophages from tumor-bearing mice, suggesting that upon C5aR1 inhibition or C5aR1 deletion, PFKM stabilization mediated by AKT2 activation was required for the M1 phenotype." (PMID 38331868, 2024).
tumor (continued). "Further, we observed no change in total AKT phosphorylation across those tumors in which AKT2 was depleted, suggesting AKT1 or AKT3 activity may compensate over time to promote tumor growth." (PMID 37894325, 2023). "When comparing the untreated MAS98.12 and HbCx39 models, we found that Akt‐pS473, Akt‐pT308, Akt1‐pS473, and Akt2‐pS474 all had an increased expression in MAS98.12, which may explain the effect of LXR activation on tumor growth observed in this model." (PMID 37341140, 2023). "The preliminary role of AKT2 in the context of tumor transformation is not for the pro-survival or pro-growth of tumor cells; however, it displays the crucial function of metabolic regulation in the HCC model of mice." (PMID 36768977, 2023). "We next sought to test if AKT2 knockout impaired tumor initiation when compared to AKT1 and AKT3 deletion, as our CRISPR-edited WM1799 cells exhibited more robust AKT2 deletion compared to the inducible knockdown lines, which did not impact tumor initiation." (PMID 37894325, 2023). "Interestingly, we found that while the AKT2 and AKT3 KO WM1799 cells developed tumors similarly to NT cells, only the AKT1 KO cells had significantly delayed tumor growth." (PMID 37894325, 2023). "Although highly homologous, the AKT isoforms exert, indeed, distinct, non-redundant effects in BC, with AKT1 displaying a tumor-initiating role and AKT2 being mainly involved in tumor progression and metastasis." (PMID 35628294, 2022). "Studies from transgenic mice suggested that Akt1 plays an important role in the initiation, development, and progression of breast tumors, whereas Akt2 has no major involvement in the process of tumor initiation but contributes to the process of tumor growth." (PMID 35892586, 2022). "AKT2 and AKT3 also have pro‐tumour functions but whether HSF1 can be regulated by these isoforms remains unknown." (PMID 35080342, 2022). "In addition, Akt2 activation induced glucose transporter 1 (GLUT1) expression, glucose uptake and lactate production, which is a common phenotypic change in tumor cells." (PMID 35454769, 2022). "We demonstrated here the ability of the Vav1-induced miR-29b to down-regulate Akt2 in MDA-MB-231 cells both in vitro and in tumor xenografts derived from MDA-MB-231 cells stably over-expressing Vav1, ascertaining the existence of a Vav1/miR-29b/Akt2 axis in these TNBC cells." (PMID 35743776, 2022). "The results of this integrative cBioPortal analysis suggest that genes AKT3, CHUK and PTEN behave like tumor suppressors, while AKT1, AKT2, EGFR, and PIK3AP1 show oncogenic behavior and are involved in enhanced activity of the EGFR-PI3K-AKT-mTOR signaling pathway." (PMID 34209611, 2021). "In conclusion, our study suggested that miR-29b-3p could influence DNA damage response by regulating the expression of DNMT3B, Bcl-2, PI3KR1, AKT2, and RBL1, thereby affecting tumor radioresistance." (PMID 34604239, 2021). "The high expression of Akt2 correlated with the histopathological differentiation, portal invasion, and the number of tumor nodules, while Akt1 did not correlate with any of these clinicopathological features." (PMID 33670268, 2021). "In both mouse models, systemic Akt2 deletion elevated insulin levels and either did not affect tumor progression or exacerbated tumor growth and metastasis." (PMID 35578699, 2021). "Consistently, ectopic expression of the myristoylated form of AKT1 (myr-AKT1) significantly repressed USP12 expression in both human and mouse tumour cells; knockdown of endogenous AKT1 or AKT2, the two major isoforms of AKT, induced higher levels of USP12 than did the control treatment." (PMID 34381028, 2021). "Based on the results from microarray hybridization and gene expression analysis, we speculated that protein kinase B β (AKT2) is a downstream protein of HSDL2, which plays an important role in the anti-tumor process induced by HSDL2 KD." (PMID 32211805, 2020).